CDK6 (cyclin dependent kinase 6)
Diseases named in the same sentence as CDK6 in open-access papers (continued):
Sharing a sentence is not in itself a finding about the gene and the disease.
anaplastic large cell lymphoma (1 paper, 2022). Anaplastic large cell lymphoma (ALCL) is a rare and aggressive peripheral T-cell non-Hodgkin lymphoma, belonging to the group of CD30-positive lymphoproliferative disorders, which affects lymph nodes and extranodal sites. "In addition, Hoareau-Aveilla C. and colleagues studied its role in NPM-Anaplastic large cell lymphoma (NPM -ALK+ ALCL) cells, where it regulates the expression of cyclin E1, CDK6, and E2F3." (PMID 36498861, 2022).
Atrophy (1 paper, 2023). Any weakening or degeneration, especially through lack of use. "Although CDK6 deficiency can cause thymic atrophy due to a block in the double-negative (DN) to double-positive (DP) stage of T cell development, there are no overt defects in immune cell development reported for CDK4-deficient mice." (PMID 37893220, 2023).
bipolar disorder (1 paper, 2018). A disorder of the brain that causes unusual shifts in mood, energy, activity levels and the ability to carry out day-to-day tasks. "In addition, genes linked to ID (TCF4, CPLX1, CDK6, KDM5B), ASD (RORA, KDM5B), and bipolar disorder (ZNF804A) were also among the 16 differentially expressed target genes." (PMID 29665782, 2018).
bone marrow fibrosis (1 paper, 2023). "Corroborating this idea, the authors show an enhancement of the Ruxolitinib effect in synergy with CDK6 inhibitor Palbociclib, significantly reducing leukocytosis, splenomegaly, and bone marrow fibrosis in Jak2V617F and MPLW515L murine models." (PMID 36910610, 2023).
cognitive deficits (1 paper, 2025). "In AD, preliminary evidence has shown FGF2 improved cognition by modulating ferroptosis and supporting neuronal survival, whereas YAP1 mitigates cognitive deficits and reverses AD pathology via CDK6 signaling or artemisinin activation." (PMID 40933191, 2025).
colon adenocarcinoma (1 paper, 2018). "Known Hsp90 clients EGFR, HER2, CDK4, CDK6, CXCR4, Akt-1, c-Raf, Survivin, ERK-5 and Integrin α2 were analyzed following the administration of KUNB31 to HT29 (colon adenocarcinoma grade II) cells." (PMID 29382832, 2018).
corticotroph adenoma (1 paper, 2024). "Martins and colleagues conducted a study to investigate the USP8 variant and its contribution to gene expression of cell cycle regulators including P27/CDKN1B, CCNE1, CCND1, CDK2, CDK4, and CDK6 in 32 corticotroph adenoma." (PMID 38862897, 2024).
cyst (1 paper, 2025). A sac-like closed membranous structure that may be empty or contain fluid or amorphous material. "Hyperandrogenism, coupled with impaired apoptosis and dysregulated cell cycle genes (e.g., CCND1, CDK6), prevents proper ovarian follicular selection and dominance, leading to cyst formation." (PMID 40725447, 2025). "For instance, MYC Proto-Oncogene (MYC) and Cyclin-Dependent Kinase 6 (CDK6) are involved in driving granulosa cell proliferation and activating ovulatory pathways, but their overexpression in the absence of proper differentiation may result in cyst formation." (PMID 40725447, 2025).
diabetic retinopathy (1 paper, 2024). "The results further confirmed that overexpression of CDK6 reversed the protective effect of sh-YTHDC1 on diabetic retinopathy in vivo." (PMID 38978074, 2024). "It suggested that the regulation of YTHDC1 in diabetic retinopathy may be related to the CDK6 methylation." (PMID 38978074, 2024).
dwarfism (1 paper, 2021).
dysplasia (1 paper, 2022). A usually neoplastic transformation of the cell, associated with altered architectural tissue patterns. "Interestingly, miR-1a-3p and Cdk6 were down- and up-regulated in dysplastic lesions, respectively." (PMID 36361810, 2022).
fibrosarcoma (1 paper, 2023). A malignant mesenchymal fibroblastic neoplasm affecting the soft tissue and bone. "To further explore the function of CDK6 and the differences between CDK6 and CDK4, we established two independent Cdk6-deficient MCA205 mouse fibrosarcoma cell lines (A43 and A57) using CRISPR/Cas9 technology." (PMID 37833461, 2023).
fungal infections (1 paper, 2025). "CDK6, in particular, plays a critical role in neutrophil-mediated defense against Candida albicans, as mice deficient in CDK6 show increased susceptibility to fungal infections." (PMID 40806591, 2025).
gliosarcoma (1 paper, 2021). A rare histological variant of glioblastoma (WHO grade IV) characterized by a biphasic tissue pattern with alternating areas displaying glial and mesenchymal differentiation (WHO). "In a comprehensive whole-genome copy number analysis of gliosarcoma, a study found EGFR amplification was uncommon, but found frequent gains of chromosome 7, which contains the EGFR locus, among other genes including CDK6, PDGF-A, and c-Met22." (PMID 34504233, 2021).
hematoma (1 paper, 2025). A hematoma is a collection of blood from a vascular structure into an extravascular space. "In the brain tissue of patients who developed CVS following a cerebral hemorrhage, CDK6 and SLC2A1 showed upregulation in the hematoma region, where they co-localized with SMA (smooth muscle actin)." (PMID 39981435, 2025).
Hepatitis (1 paper, 2020). Inflammation of the liver.
IgA nephropathy (1 paper, 2020). "Furthermore, inhibition of miR-29b-3p increased CDK6 expression and activation of the NF-κB signaling pathway to promote inflammation in IgA nephropathy." (PMID 31955152, 2020).
infarction (1 paper, 2022). A localised pathological necrosis of tissue resulting from obstruction of the blood supply usually by a thrombus, an embolus, or vascular torsion. "A previous study has also shown the down-regulation of CDK6 in the penumbra surrounding the infarction region comparing with control, which supports the inverse association between expression of CDK6 and the risk of AS and AIS in our TWAS analysis." (PMID 35449099, 2022).
ischemic stroke (1 paper, 2018). A stroke disorder caused by obstruction of blood flow to the brain, due to thrombotic (local blood clot formation) or embolic (due to a blood clot or other material traveling from another site) event. "In summary, miR-424 levels in peripheral immune cells has diagnostic potential for ischemic stroke, and might affect the severity of acute stroke by depressing the peripheral inflammatory response through CDK6-dependent pathway in lymphocytes or CDK6-independent pathway neutrophils." (PMID 29675290, 2018).
keloid (1 paper, 2022). An irregularly shaped, elevated mark on the skin caused by deposits of excessive amounts of collagen during wound healing. "Otherwise, Studies have confirmed that circ_101238/miR-138-5p/CDK6 axis plays a potential regulatory role in keloid." (PMID 35068324, 2022).
kidney cancer (1 paper, 2024). Primary or metastatic malignant neoplasm involving the kidney. "Targeting CDK4 and CDK6, either separately or in combination with already approved treatments, may improve therapeutic outcomes in patients with kidney cancer." (PMID 39058879, 2024).
leiomyosarcoma (1 paper, 2019). An uncommon, aggressive malignant smooth muscle neoplasm, usually occurring in post-menopausal women. "Out of all the leiomyosarcoma patients, 65.7% were positive for both CDK4 and CDK6." (PMID 30804704, 2019). "Comparison of uterine vs nonuterine leiomyosarcoma showed the following: Uterine tumour samples (n=46) were positive for CDK4, CDK6, and p-Rb in 65.2%, 87.2%, and 73.9%, respectively; 30.4% expressed ≤10% p16 protein." (PMID 30804704, 2019).
lipoma (1 paper, 2017). A benign, usually painless, well-circumscribed lipomatous tumor composed of adipose tissue. "PFN2 (profilin 2), BTG1 (BTG anti-proliferation factor 1), LPP (LIM domain containing preferred translocation partner in lipoma) and CDK6 (cyclin dependent kinase 6) came to prominence as significant genes that have important effects in the cancer progression." (PMID 28981542, 2017).
lymphoid tumor (1 paper, 2013). "In conjunction with a previous report of AKT-induced thymoma formation, our human data indicate a role for CDK6 not only in B-lymphoid disease, but also in T-lymphoid tumor formation." (PMID 23948297, 2013). "Our model makes a testable prediction: high CDK6 expression in a lymphoid tumor should confer a growth advantage only when expression of p16INK4a is disrupted." (PMID 23948297, 2013). "The cyclin-dependent kinase CDK6 promotes cell-cycle progression and is expressed at high levels in lymphoid tumors." (PMID 23948297, 2013).
malignant pleural mesothelioma (1 paper, 2022). A malignant neoplasm that arises from mesothelial cells in the pleura and shows a diffuse growth pattern. "In malignant pleural mesothelioma (MPM), miR-206 targets CDK6 and arrests the cell cycle at the G1/S phase." (PMID 36233210, 2022).
mast cell leukemia (1 paper, 2016). Mast cell leukemia is a malignant form of systemic mastocytosis (SM) characterized, most of the time, by the presence of circulating mast cells. "CDK6 siRNAs were transfected in HMC1.1, a mast-cell leukemia carrying an endogenous point mutation in the juxtamembrane domain of KIT, and TF-1 cells stably transfected with the classical KIT D816V mutation." (PMID 27323399, 2016).
monocytic leukemia (1 paper, 2010). "We found that celastrol could arrest human monocytic leukemia cells U937 at G0/G1 phase, this arrest accompanied by down-regulation of Cyclin D1, Cdk4, Cdk6, and Cdk2." (PMID 20398364, 2010).
myelofibrosis (1 paper, 2023). A partial or complete replacement of the bone marrow stroma by fibrous tissue. "Moreover, CDK6 expression is evidently increased in MPN/myelofibrosis haematopoietic progenitor cells and its overexpression is related to diabetes, inflammatory diseases, and cancers." (PMID 36342274, 2023).
myeloid neoplasm (1 paper, 2023). Proliferation of myeloid cells originating from a primitive stem cell. "While the CDK6 gene is known to be a critical regulator of normal and leukemic stem cells, the involvement of BCL11B in myeloid neoplasms is unusual." (PMID 37046792, 2023).
ovarian tumours (1 paper, 2024). "CDKN2A (p16INK4a), which is known to inhibit CDK4 and CDK6, was deleted or downregulated in 21% of the ovarian tumours." (PMID 38612869, 2024).
Pain (1 paper, 2019). An unpleasant sensory and emotional experience associated with actual or potential tissue damage, or described in terms of such damage. "Collectively, these results indicate that an epigenetic regulatory pathway involving PKIA-AS1 and CDK6 mediates SNL-induced neuropathic pain." (PMID 30873006, 2019).
Pca (1 paper, 2020). "The protein expression levels of CDK2, CDK4, CDK6, and phospho-Rb (Ser807/811) declined in quiescent Pca cells, and almost all of them began to recover at 12 and 16 h after quiescent LNCaP and PC-3 cell re-entry into the cell cycle, respectively." (PMID 33392189, 2020).
periodontitis (1 paper, 2023). An acute or chronic inflammatory process that affects the tissues that surround and support the teeth. "CDK6 also inhibits the proliferation of periodontal ligament cells (PDLCs) by regulating the cell cycle in periodontitis." (PMID 36639776, 2023).
pleural mesothelioma (1 paper, 2020). A neoplasm that arises from the mesothelial cells of the pleura. "In CDKN2A-mutated malignant pleural mesothelioma cell lines and in a mouse model, the inhibition of CDK4/CDK6 was shown to suppress cell viability and tumour growth." (PMID 32526924, 2020).
primary effusion lymphoma (1 paper, 2024). A large B-cell lymphoma located in the body cavities, characterized by pleural, peritoneal, and pericardial fluid lymphomatous effusions and that is always associated with human herpes virus-8 (HHV-8). "Collectively, our data indicate that targeting CDK6 and CAD is a promising strategy against γ-herpesvirus-induced primary effusion lymphomas." (PMID 38365882, 2024). "Correspondingly, genetic depletion or pharmacological inhibition of CDK6 and CAD potently impeded KSHV lytic replication and thwarted tumorigenesis of primary effusion lymphoma (PEL) cells in vitro and in vivo." (PMID 38365882, 2024).
pulmonary disorder (1 paper, 2022). "Based on pathway enrichment analysis, genes altered in BPD blood cells were mainly enriched in cell cycle regulation and arrest (e.g., PPP2CA, RBL2, CENPU, CCNY, CDK6) and pulmonary disorder and developmental disorders (e.g., AGER, ITGA6, CA4, BACH2, IGFBP2, BMPR2, SKI, DAB2)." (PMID 35484630, 2022).
rectum adenocarcinoma (1 paper, 2022). An adenocarcinoma arising from the rectum. "Heterozygous amplifications of ETS2 and CDK6 in TGCT; CDK6 in GBM; E2F1 and ID1 in rectum adenocarcinoma (READ); and SP1, CDK4, and MDM2 in ACC were all greater than 70%." (PMID 35911954, 2022).
retina degeneration (1 paper, 2014). "SNTB2 is necessary for eye development in Drosophila, SLC1A2 is a glutamate transporter and glutamate reduction was observed in Müller cell in rd1 retina, and CDK6 is involved in retina degeneration in mice." (PMID 24581223, 2014).
schwannoma (1 paper, 2022). A benign, usually encapsulated slow growing tumor composed of Schwann cells. "MA showed that miR-29a could target CDK6 and down-regulate JNK and p38/MAPK/ERK signaling pathways, thereby inhibiting the proliferation of schwannoma." (PMID 35113040, 2022).
skin squamous cell carcinoma (1 paper, 2022). A carcinoma arising from the squamous cells of the epidermis. "In skin squamous cell carcinoma, miR-365a-3p plays an oncogenic role by downregulating nuclear factor IB to promote CDK6 and CDK4 expression, leading to Rb phosphorylation and tumor progression." (PMID 35682793, 2022).
synovial sarcoma (1 paper, 2018). "Relative expressions of CDK4 and CDK6 were compared with β-actin in different synovial sarcoma cell lines." (PMID 29670090, 2018).
thyroid follicular cancer (1 paper, 2021). "MiR-191 displays tumor-type specific roles in tumorigenesis, as miR-191 inhibits cyclin-dependent kinase 6 (CDK6) expression in thyroid follicular cancer." (PMID 34506539, 2021).
tongue tumors (1 paper, 2021). "For instance, we observed a fusion of CDK6 in one of the tongue tumors while it has previously been associated predominantly only with ALL." (PMID 33670576, 2021).
urothelial carcinoma (1 paper, 2022). A malignant neoplasm derived from the transitional epithelium of the urinary tract (urinary bladder, ureter, urethra, or renal pelvis). "We selected two urothelial carcinoma cell lines, T24 and 5637, with different CDK6 protein expression levels, to observe the inhibitory effect of CDK4/6 inhibitors." (PMID 35463324, 2022). "IHC staining for CDK6 protein in urothelial carcinoma is proposed as a promising screening platform for CDK4/6 inhibitor targeted therapy." (PMID 35463324, 2022). "The data from public sources indicate poor prognosis in urothelial carcinoma cases with high CDK6 mRNA levels." (PMID 35463324, 2022). "Immunohistochemistry (IHC) is simple and easy to perform and can be used to screen urothelial carcinoma cases with high CDK6 expression in clinical practice." (PMID 35463324, 2022). "In this study, we observed the activity of CDK6 in urothelial carcinoma cases and defined about 28% (24/85) CDK6 high expression cases with unknown CDK4 state." (PMID 35463324, 2022). "Furthermore, studies have shown that CDK6 expression is elevated in urothelial carcinoma tissue compared to the surrounding urothelium, thus presenting a case for performing CDK4/6 inhibitor targeted research in urothelial carcinoma." (PMID 35463324, 2022). "Furthermore, we found that urothelial carcinoma cell lines with higher CDK6 expression levels displayed greater sensitivity to CDK4/6 inhibitors than cells with lower expression levels." (PMID 35463324, 2022). "Furthermore, since CDK6 display both kinase activity in cell cycle regulation and transcriptional regulation activity, it will be useful to investigate the oncogenic mechanism of CDK6 in urothelial carcinoma by either knockdown or overexpression of CDK6 in vitro experiment in the future." (PMID 35463324, 2022). "A study involving 31 urothelial carcinoma cases showed higher CDK6 expression levels in the BLCA tissues than in adjacent non-neoplastic tissues, suggesting that CDK6 could be a potential therapeutic target for urothelial carcinoma." (PMID 35463324, 2022).